ICAM1 (intercellular adhesion molecule 1)
Diseases named in the same sentence as ICAM1 in open-access papers (continued):
Sharing a sentence is not in itself a finding about the gene and the disease.
COVID-19 (continued). "Conversely, there was a significant 2.943-fold increase in ACE2 expression and significantly altered expression of pro-inflammatory and pro-coagulation genes, including 1.306-fold for F3 and 0.548-fold for ICAM1 (p < 0.05) in patients with COVID-19 compared with healthy controls." (PMID 36560757, 2022). "The increased expression of endothelial cell adhesion molecules like ICAM1 is related to the severity of COVID-19 and may lead to coagulation dysfunction." (PMID 34177566, 2021). "Amongst T-cell and monocytes/macrophages, some immune-stimulatory or auto-regulatory interactions were seen (CTLA4 or CD28/CD80 or CD86, CCL5/CCR5), but specific epithelial to T-cell interactions in critical COVID-19 were limited to pro-inflammatory ICAM1-mediated interactions." (PMID 33473155, 2021). "•ICAM-1 serum levels represent an additional, initial screening marker for COVID-19." (PMID 33585030, 2021). "Furthermore, six core gene targets including CAT, NOS2, CXCR3, MAPK1, GPT, and ICAM1 of VA against CHOL/COVID-19 were identified using Cytoscape tool." (PMID 34176789, 2021). "Our data revealed a significantly higher mean numbers of ICAM1+ CECs in convalescent COVID-19 with or without cardiovascular risk and non-COVID-19 cardiovascular risk groups." (PMID 33752798, 2021). "This suggests that ICAM-1 could be used as an additional biomarker of COVID-19 since inflammation plays a crucial role in the pathogenesis of the disease." (PMID 33585030, 2021). "Additionally, increased expression of ICAM1 in COVID-19 patients contributes to replication of SARS-CoV-2 and provides a favorable environment for its survival in humans." (PMID 34975885, 2021). "Others have reported that the lymphopenia associated with COVID-19 could be a consequence of pulmonary recruitment and entrapment of lymphocytes, due to modification of adhesion molecules (CD44, LFA-1 and ICAM-1)." (PMID 33718270, 2021). "Positive aPL sera from COVID-19 patients induced upregulation of the cell adhesion molecules E-selectin, vascular cell adhesion molecule 1 (VCAM-1), and intracellular adhesion molecule 1 (ICAM-1) in HUVECs, which was abolished by total IgG depletion from the COVID-19 sera." (PMID 34977191, 2021). "The analysis of COVID-19 extended interactome indicates several membrane bound gene/proteins (i.e., ICAM1, EGFR, ERBB2, APP, ADR2, FAS, CDH1, and MAPT), whose activity and/or expression could be affected by SARS-CoV-2 challenge." (PMID 33123533, 2020). "Moreover, as circulating spike protein in COVID-19 patients’ blood has been reported, we also incubated ECs with spike protein (recombinant spike extracellular domain-His-tag protein, original Wuhan strain) and observed increased ICAM1 expression at 24 h." (PMID 39739157, 2024). "Previous studies have suggested that ICAM-1 triggers cell-to-cell transmission of HIV-1 or HTLV-1, that SARS-CoV-2 shares several features with these viruses via interactions between cells, and that SARS-CoV-2 cell-to-cell transmission is associated with COVID-19 severity." (PMID 37719701, 2023). "In this study, we analyzed ICAM-1 as an endothelial inflammatory adhesion molecule as a biomarker that could be used as a prognostic factor for surgical patient outcomes and determined its relationship to COVID-19 and other related factors." (PMID 38465016, 2023). "Previous studies suggested that VCAM-1, and intracellular cell adhesion molecule-1 (ICAM-1) might promote the interaction between leukocytes and endothelial cells, by serving as ligands for integrins, and thus may play an important role in COVID-19 pathogenesis." (PMID 35836945, 2022). "Higher circulating DAMPs (e.g., ds-DNA, HMGB1), and endothelial proteins such as E-selectin, PECAM-1, or ICAM-1 provide a mechanistic link for the prothrombotic state and hepatic portal thrombosis, pulmonary thrombosis induced by LA, which is similar to COVID-19 autopsies." (PMID 35502320, 2022).
COVID-19 (continued). "This absence of discrimination of VEGF-A, according to the prognosis of COVID-19 patients, has already been described in small cohort studies, contrary to other endothelial biomarkers, such as angiopoietin-2 or the Intercellular Adhesion Molecule type 1 (ICAM-1)." (PMID 35956186, 2022). "Moreover, a retrospective study in China of 39 patients with COVID-19 and 32 controls showed that the former had significantly increased levels of ICAM-1 and other endothelial adhesion molecules, which may contribute to coagulopathy." (PMID 33585030, 2021). "Therefore, ICAM1 protein can be considered a key target for treatment of COVID-19 patients." (PMID 34975885, 2021). "When we analyzed their endothelial activation hallmarks by disease severity, both convalescent COVID-19 patients who recovered from moderate symptoms (p=0.006) and non-COVID-19 patients with cardiovascular risks (p=0.0148) had significantly higher numbers of ICAM1+ CECs than healthy controls." (PMID 33752798, 2021). "Moreover, a significant increase in expression of endothelial cell adhesion molecules e.g., intercellular adhesion molecule 1 (ICAM1) in patients with severe COVID-19, is associated with COVID-19 severity and may cause coagulation disorders." (PMID 34975885, 2021). "At three months post infection, high levels of D-Dimer, E-Sel, ICAM-1, and VCAM-1 were observed, according to a previous study reporting that, at 3 months after COVID-19, D-Dimer level was increased in 15% of the subjects who had recovered from COVID-19." (PMID 41226453, 2025). "The consistent increase in ICAM1, MCL1, IL1β, and S100A12 expression in neutrophils from severe alive to severe dead patients underscores the critical role of neutrophils in COVID-19 severity." (PMID 39928675, 2025). "The COVID-19 high-stage-specific markers (i.e., FOS, CXCL8, HLAA, JAK3, ICAM1, and H2BC4) were overexpressed in higher-stage samples, that is, increased expression levels of the markers were observed in asymptomatic to critical samples." (PMID 41155463, 2025). "Compared with the healthy group, COVID-19 patient group displayed the significantly lower expression level of BCL2, but significantly higher expression levels of MMP9, ICAM1, and TLR4." (PMID 41411324, 2025). "Biomarkers such as IL-6, IL-8, PAI-1, and ICAM-1, key to class designation in hyper- and hypo-inflammatory ARDS, were notably less class separating in severe COVID-19 subtypes, potentially rendering them less useful in phenotyping this patient population." (PMID 38383504, 2024). "After 6 months of infection, PLWH exhibited significantly higher serum levels of ACE2, VCAM-1, and ICAM-1 (P < 0.01, respectively) compared to PNLWH with COVID-19." (PMID 39669584, 2024). "HPMVEC exposed to normal serum showed very minimal ICAM-1 and NLRP3 subunit expression (green fluorescence arising from secondary antibody) as compared to cells treated with COVID-19 serum." (PMID 38771750, 2024). "Patients with COVID-19-induced ARDS have higher serum levels of endothelial damage markers such as angiopoietin-2, intercellular adhesion molecule-1, vascular cell adhesion molecule-1, P-selectin, and E-selectin than patients with other types of ARDS." (PMID 39408067, 2024). "Regarding surrogate endothelial markers, plasma soluble intercellular adhesion molecule 1 (sICAM-1) levels were higher in the two groups of ARDS patients (p < 0.05), while sE-selectin levels were higher in the non-COVID-19 ARDS patients (p < 0.01)." (PMID 39408968, 2024). "Here we assessed the endothelial inflammation (i.e., the pro-inflammatory phenotype of ECs) by monitoring ICAM-1, NLRP3 and P-selectin in HPMVECs in an in vitro COVID-19 model." (PMID 38771750, 2024). "This study found that there are activated endothelial cells and high levels of biomarkers of blood vessel damage (ICAM-1, ANGPT-2, IL-1β) in severe COVID-19 cases." (PMID 36992415, 2023).
COVID-19 (continued). "Recently Angiopoietin-2 (Ang-2) and soluble intercellular adhesion molecule-1 (ICAM-1), were identified as markers of pulmonary endothelial injury in COVID-19 ARDS." (PMID 36675351, 2023). "Another study showed that in the serum of COVID-19 patients (n = 250) VCAM-1 and ICAM-1 levels positively correlated with SARS-CoV-2 RNAemia." (PMID 36941580, 2023). "With the World Health Organization having recently updated case definitions to suspect, probable, and confirmed, this study aimed to measure the mean value of intercellular adhesion molecule 1 (ICAM-1) and its relation to suspected COVID-19." (PMID 38465016, 2023). "The levels of the coagulation markers intercellular adhesion molecule-1 (ICAM-1) and E-selectin were consistently upregulated in post-COVID-19 female patients, in contrast to those of vascular cell adhesion molecule-1 (VCAM-1), P-selectin, and chemokine IL-8." (PMID 37896963, 2023). "Inversely to P-selectin and IFN-γ, vaccination was in positive correlation with E-selectin, ICAM-1, and VCAM-1 in post-COVID-19 male patients." (PMID 37896963, 2023). "The elevated plasma levels of adhesion molecules, such as ICAM-1 and VCAM-1, vascular adhesion protein-1, and vascular endothelial growth factor, has been reported for severe and moderate COVID-19 patients." (PMID 36674700, 2023). "The findings showed that compared to healthy controls, patients with COVID-19 had significantly higher levels of interleukins 1α, 2, 6, 7, 8, 10 and 15, CRP, SAA, ICAM-1, VCAM-1, CXCL10, CCL3, CCL26, IFN-γ, TNF-α, bFGF, PlGF, and Flt-1." (PMID 35958594, 2022). "Genes whose expressions were altered in endothelial cells under the influence of COVID-19 included TIMP1, MMP2, MMP11, VWF, ICAM1, and ICAM2, which affect coagulation and the development of inflammation." (PMID 36551272, 2022). "The top six anti-COVID-19 core targets, IL-6, PPARG, MAPK3, PTGS2, ICAM1, and MAPK1, were molecularly docked with the three key active phytomolecules of Kochiae Fructus." (PMID 35992697, 2022). "In the present cohort of COVID-19 patients, thrombomodulin, IL-6, FVIII, VWF:Ag, sEPCR, sC5b9, tPA, PAI-1 activity, C4, ICAM-1 and VCAM-1 plasma levels were higher than normal ranges, in line with previous studies that included patients with a severe disease." (PMID 36143072, 2022). "We incubated HLMVEC for 24 hr with 30% patient plasma obtained from severe COVID-19 patients who were admitted to the ICU and analyzed the cells for the expression of E-selectin, VCAM-1, ICAM-1, and IL-6." (PMID 35837388, 2022). "using serum from a large cohort of COVID-19 patients found that the surface expression of E-selectin, VCAM-1 and ICAM-1 were around 2, 4 and 3-fold increase in HUVEC compared to control serum." (PMID 35837388, 2022). "ICAM-1 and VCAM-1, soluble markers of endothelial inflammatory activation, rise in severe COVID-19 cases." (PMID 36430566, 2022). "Two genes, ICAM1 and ICAM5, belonging to the intercellular adhesion molecule family, showed effects on COVID-19 severity in our study." (PMID 35772218, 2022). "The PPI network analysis reveals that multiple targets, including IL-6, PPARG, MAPK3, PTGS2, ICAM1, MAPK1, etc., are involved in the anti-COVID-19 effects of Kochiae Fructus’ active phytomolecules." (PMID 35992697, 2022). "Ang-2, ICAM-1 and E-selectin were lower in classical ARDS than in COVID-19-related ARDS (all p < 0.001)." (PMID 33608030, 2021). "Seven core targets of vitamin A against COVID-19, including CAT, EGFR, ICAM1, IL10, MAPK1, MAPK14, and PRKCB, have been detected." (PMID 34335237, 2021). "The IHC analysis showed increased expression of caspase-1, ICAM-1, IL-1β, IL-6, MMP-9, TNF-α, and other markers in the hearts of COVID-19 patients." (PMID 34804033, 2021). "We also found an increased expression of CD63, ITGB2, CD37, CD2 and IL23R markers and the reduction in CXCR4, CD69, CD48, ICAM1 and S100A10 markers in COVID-19-derived NK-T cells compared to controls." (PMID 34944610, 2021).
COVID-19 (continued). "RNA expression of ICAM1 and PFKFB3 in the blood plasma of patients with severe COVID-19 and healthy controls was measured by qRT-PCR." (PMID 33520118, 2021). "COVID-19 ARDS is characterized by an early pulmonary endothelial injury, as detected by Ang-2 and ICAM-1." (PMID 33608030, 2021). "Expression of ICAM1 and PFKFB3 was significantly induced in severe-COVID-19 patients compared with that in healthy controls." (PMID 33520118, 2021). "Based on our results, we suggest that controlling high-severity-specific markers (FOS, CXCL8, HLA-A, JAK3, ICAM1, and H2BC4) and low-severity-specific markers (IL1B, CD3D, CD4, CCL5, and SNRPB) may prevent COVID-19 progression." (PMID 41155463, 2025). "Biological analysis revealed significant associations between certain PACS symptoms and biomarkers of viral activation (IFNγ, IP-10), COVID-19 severity (CD163) and vascular activation (VCAM-1, ICAM-1), mainly in subjects whose symptoms had lasted less than a year." (PMID 40449327, 2025). "JAK3, ICAM1, and H2BC4 were identified as markers of higher COVID-19 severity." (PMID 41155463, 2025). "In parallel, adhesion molecules, early markers of endothelial activation/dysfunction, such as selectins (E-, P-, and L-selectin), soluble intercellular adhesion molecule 1 (ICAM-1), and vascular adhesion molecule 1 (VCAM-1), are also elevated in plasma samples from COVID-19 patients." (PMID 38494528, 2024). "Compared with the lungs of patients with non-pulmonary diseases, ICAM-1 levels in patients with COVID-19 were significantly higher." (PMID 38771750, 2024). "IL-6 and SP-D are correlated with both BMI and age, while complement C5a, E-selectin, ICAM-1, MCP-1, Tie-2, and vWF levels were associated with age in patients with critical, but not severe COVID-19." (PMID 39507250, 2024). "Interestingly in ILC1 cells, ICAM1, PIK3AP1, STAT5A, TGFB1 and FAM65B genes show the highest degree of network rewiring across healthy vs COVID-19 correlation networks." (PMID 39026668, 2024). "Nevertheless, the interactions arising from ICAM-1 are not explicitly recognized as indispensable in the case of COVID-19." (PMID 37719701, 2023). "In the first paret, only the presence or absence of COVID-19 was a factor related to serum ICAM-1 levels at baseline." (PMID 38465016, 2023). "Similarly, circulating levels of endothelial markers such as ICAM-1, VCAM-1, and prothrombotic markers such as vWF or P-selectin have been reported in this cohort of COVID-19 ARDS patients." (PMID 37283766, 2023). "Another trend observed in this study was that the average level of ICAM-1 was slightly higher but not statistically significant in patients with a confirmed COVID-19 case who underwent surgery." (PMID 38465016, 2023). "Moreover, circulating levels of P-selectin, E-selectin, soluble intercellular adhesion molecule-1 (ICAM-1), thrombomodulin, angiopoietin-2, and plasminogen activator inhibitor-1 (PAI-1) are augmented in COVID-19." (PMID 37108759, 2023). "In the severe COVID-19 group, we observed a hyperinflammatory state, as judged by increased concentration of cytokines (IL-1α, IL-4, IL-6, IL-10 and IL-17A), chemokines (IP-10 and MIP-1β), and adhesion markers (E-selectin and ICAM-1)." (PMID 37441066, 2023). "Thus, the exposure of platelets co-cultured with endothelial cells to COVID-19 D4 TPE plasma induced membrane overexpression of platelet and endothelial activation markers, namely CD62P and ICAM-1, respectively." (PMID 37215546, 2023). "The elevated levels of vascular endothelial activation markers, including von Willebrand factor (VWF), plasminogen activator inhibitor, intercellular adhesion molecule-1 (ICAM-1), and vascular cell adhesion molecule-1 (VCAM-1), have been observed in patients with COVID-19." (PMID 36551272, 2022).
COVID-19 (continued). "At first sight, the association of elevated C5a, ICAM-1 and VCAM-1 concentration on admission with ICU admission or 30-day mortality did not point towards a specific feature of COVID-19, as it was observed in cases and controls in the present study." (PMID 36203596, 2022). "The increased production of RAGE ligands in CKD and COVID-19 may therefore activate leukocyte RAGE and enhance Mac-1 binding activity to ICAM-1 on endothelial cells and additional parenchymal cells in the kidney." (PMID 36017003, 2022). "Among elevated plasma inflammatory mediator levels; CRP, ICAM-1, SAA, VCAM-1, CXCL10, IL-7, IL-10 and Flt-1 may suggest the severity of COVID-19." (PMID 35958594, 2022). "Moreover, in TNF-α activated monocytes, ITF3756 reduces the expression of additional biomarkers of severe COVID-19, such as PTX3, ICAM-1, S100A12, PD-L1 and MMP9, further supporting a potential role for this molecule in the treatment of the disease." (PMID 35592335, 2022). "Compared to the healthy controls, patients with COVID-19 had significantly higher circulating concentrations of 19 inflammatory mediators, namely interleukins 1α, 2, 6, 7, 8, 10 and 15, CRP, SAA, ICAM-1, VCAM-1, CXCL10, CCL3, CCL26, IFN-γ, TNF-α, bFGF, PlGF and Flt-1 (P < 0.05)." (PMID 35958594, 2022). "Soluble forms of ICAM-1, VCAM-1 and E-selectin are used as biomarkers for endothelial cell activation, and several studies demonstrate increased concentrations of these proteins in COVID-19 patients related to the disease severity." (PMID 36203596, 2022). "•ICAM-1 levels in patients with DFU in the COVID-19-positive group were significantly higher than the COVID-19-negative group." (PMID 33585030, 2021). "In this study, we were able to demonstrate that in critically ill COVID-19 patients, circulating P-selectin, E-selectin, Ang-2, ICAM-1, and vWf levels on ICU admission are elevated in non-survivors compared to survivors." (PMID 33477776, 2021). "Additionally, the anti-CHOL/COVID-19 effect of VA was controlled by 3 core genes, including ICAM1, NOS2, and CAT, suggesting the possible therapeutic and immunotherapeutic targets for treating COVID-19 or CHOL/ COVID-19." (PMID 34176789, 2021). "Our results indicated that vitamin D treatment shortened the hospitalization period, decreased the mortality rate, and that the effect of vitamin D in COVID-19 might involve regulation of INOS1, IL1B, IFNg, cathelicidin-LL37, and ICAM1." (PMID 34836309, 2021). "In general, FCER1g, ICAM1, LAT, LCN2, and PLAU may be the main immune genes that are regulated by COVID-19 to induce olf and neurological dysfunction." (PMID 34504502, 2021). "The correlation analysis of specific serum biomarkers with 25OHD indicated that the vitamin D action in COVID-19 might involve regulation of INOS1, IL1B, IFNg, cathelicidin-LL37, and ICAM1." (PMID 34836309, 2021). "Moreover, the expression of ICAM1, NOS2, and CAT was increased in CHOL/COVID-19, while the survival rate was low, although these genes were only marginally increased." (PMID 34176789, 2021). "ICAM1 and PFKFB3 were the most significantly upregulated genes in our meta-analysis and could be employed as biomarkers in patients with severe COVID-19." (PMID 33520118, 2021). "ICAM-1 levels in patients with DFU in the COVID-19-positive group were significantly higher than those in the COVID-19-negative group (median 317.2 vs 149.2, respectively; p < 0.001)." (PMID 33585030, 2021). "We unexpectedly observed that, relative to healthy control subjects, patients with severe COVID-19 did not have significantly elevated markers of endothelial injury, such as Ang-2 and ICAM-1." (PMID 34214123, 2021). "A novel finding from our study is that ICAM-1 levels were significantly elevated in patients with COVID-19 with DFUs compared with patients without COVID-19." (PMID 33585030, 2021). "Similar levels of ICAM-1, thrombomodulin, and P-selectin levels were observed between COVID-19 positive and negative patient cohorts." (PMID 34491250, 2021).